RNU4-67P (RNA, U4 small nuclear 67, pseudogene)
Gene: Small nuclear RNA gene on chromosome 12 (25,404,288 to 25,404,428, reverse strand). Ensembl gene ENSG00000201439.
Homologues: Orthologues: chimpanzee U4 (99% identical), macaque U4 (96% identical). Paralogues in human: RNU4-13P (89% identical), RNU4-7P (88% identical), RNU4-68P (86% identical), RNU4-58P (85% identical), RNU4-44P (84% identical), RNU4-23P (84% identical), RNU4-42P (84% identical), RNU4-45P (84% identical), RNU4-56P (84% identical), RNU4-8P (84% identical), RNU4-16P (83% identical), RNU4-20P (83% identical), and 81 more.